DYNLT3 (dynein light chain Tctex-type 3)
Description:
Acts as one of several non-catalytic accessory components of the cytoplasmic dynein 1 complex that are thought to be involved in linking dynein to cargos and to adapter proteins that regulate dynein function. Cytoplasmic dynein 1 acts as a motor for the intracellular retrograde motility of vesicles and organelles along microtubules. Probably binds BUB3 as part of transport cargo. Required for the efficient progression through mitosis (By similarity).
Synonyms: TCTE1L; TCTEX1L; RP3
Tractability: PROTAC: ubiquitination databases record sites on it; its protein half-life has been measured.
Gene: Protein-coding gene on chromosome X (37,836,757 to 37,847,571, reverse strand). Ensembl gene ENSG00000165169.
Subcellular location: Nucleus; Cytoplasm, cytoskeleton; Chromosome, centromere, kinetochore
Gene Ontology:
Molecular function: identical protein binding; protein binding; dynein intermediate chain binding
Biological process: intraciliary retrograde transport; microtubule-based movement; positive regulation of intracellular transport; positive regulation of mitotic cell cycle spindle assembly checkpoint; regulation of mitotic cell cycle; positive regulation of mitotic cell cycle
Cellular component: cytoplasmic dynein complex; kinetochore; cilium; cytoplasm; dynein complex; male germ cell nucleus; cytoskeleton; mitotic spindle astral microtubule; nucleus
Homologues: Orthologues: macaque DYNLT3 (100% identical), dog DYNLT3 (97% identical), pig DYNLT3 (95% identical), guinea pig DYNLT3 (93% identical), mouse Dynlt3 (91% identical), rat Dynlt3 (86% identical), zebrafish dynlt3 (67% identical), tropical clawed frog DYNLT3 (62% identical). Paralogues in human: DYNLT1 (53% identical), DYNLT5 (27% identical), DYNLT2 (22% identical), DYNLT2B (22% identical), DYNLT4 (16% identical).
Diseases named in the same sentence as DYNLT3 in open-access papers:
DYNLT3 is named in the same sentence as 22 diseases in open-access papers, as found by Europe PMC text mining. Sharing a sentence is not in itself a finding about the gene and the disease. The quoted sentences say what the papers report.
ovarian carcinoma (4 papers, 2021 to 2023). A malignant neoplasm originating from the surface ovarian epithelium. "Consistent with our study, several studies demonstrated that DYNLT3 was upregulated in salivary gland adenoid cystic carcinoma, ovarian cancer and breast cancer." (PMID 37260179, 2023). "DYNLT3 exerts pro-tumoral effects on Ovarian cancer through promoting cell proliferation, migration and invasion." (PMID 35057823, 2022). "Recently, dynein light chain Tctex-type 3 has been reported to foster ovarian cancer through promoting cell proliferation, migration, and invasion." (PMID 34456862, 2021). "However, in salivary gland adenoid cystic carcinoma, DYNLT3 was predicted to be a candidate oncogene, and in our previous ovarian cancer research, DYNLT3 also showed tumor-promoting effects by facilitating cell proliferation and invasion in ovarian cancer cells." (PMID 35965516, 2022).
breast carcinoma (3 papers, 2020 to 2023). "This research aims to elucidate the role and the underlying molecular pathways of DYNLT3 on breast cancer tumorigenesis." (PMID 37260179, 2023). "Our results demonstrated that age‐associated gene DYNLT3 may function as a tumor promoter in breast cancer by controlling the EMT process." (PMID 37260179, 2023). "DYNLT3 may function as a tumor‐promotor of age‐associated breast cancer, which is expected to provide experimental basis for new treatment options." (PMID 37260179, 2023). "Notably, recent bioinformatics research has indicated that DYNLT3, as one of the aging‐associated genes, was upregulated in the human mammary carcinoma." (PMID 37260179, 2023). "The 15 cases of breast cancer, 15 cases of breast fibroids, and 15 cases of normal tissues was used to detect differential expression of DYNLT3 protein by IHC staining." (PMID 37260179, 2023). "Animal experiments further confirmed that silence of DYNLT3 attenuated breast cancer growth in vivo." (PMID 37260179, 2023). "In the present study, we found that DYNLT3 expression was upregulated in breast cancer tissues and cells." (PMID 37260179, 2023). "The expression of DYNLT3 was found to be highest in breast cancer tissues by IHC staining, and higher in breast fibroids than in normal tissues." (PMID 37260179, 2023). "The transcription and translation levels of DYNLT3 among the four breast cancer cell lines were also detected by qRT‐PCR and Western blotting." (PMID 37260179, 2023). "The loss‐ and gain‐of‐function experiments was performed to explore the character of DYNLT3 in breast cancer." (PMID 37260179, 2023). "Nevertheless, studies of DYNLT3 action in tumors are very limited, especially in terms of its function and specific mechanism on the occurrence and development of breast cancer are still indistinct." (PMID 37260179, 2023). "Our results showed that the apoptosis rate was reduced in DYNLT3‐overexpressed MDA‐MB‐231 breast cancer cells, and reversed in DYNLT3‐knockdown MDA‐MB‐231 and MCF‐7 breast cancer cells." (PMID 37260179, 2023). "Sustaining cell proliferation is one of the phenotypes of malignancy, DYNLT3 upregulation promoted proliferative ability of breast cancer cells." (PMID 37260179, 2023). "As a result, the present research aimed to discover the potential mechanism of DYNLT3 on breast cancer cell growth and development." (PMID 37260179, 2023). "The IHC score of the DYNLT3 protein was highest in breast cancer tissues; besides, the IHC score of breast fibroid tissue was relatively greater than that of the normal control group." (PMID 37260179, 2023). "The migratory and invasive capacities were regulated in breast cancer cells with DYNLT3 expression." (PMID 37260179, 2023). "Additionally, the expression of the DYNLT3 protein in breast fibroids and breast cancer tissues was significantly higher than that of normal breast tissues, and the expression of DYNLT3 in breast cancer tissues was relatively highest among the three tissues." (PMID 37260179, 2023). "Besides, the tumor formation of breast cancer cells in nude mice was inhibited by reducing DYNLT3 expression." (PMID 37260179, 2023). "DYNLT3 expression was highly rising in both breast cancer tissues and cells." (PMID 37260179, 2023). "Furthermore, the indicators of the EMT process in breast cancer cells were altered by the level of DYNLT3." (PMID 37260179, 2023). "The differential expression of DYNLT3 among breast cancer, breast fibroids, and normal tissues, as well as in various breast cancer cell lines were detected by immunohistochemical staining, real‐time quantitative reverse transcription‐PCR and Western blotting, respectively." (PMID 37260179, 2023). "Whether the expression of DYNLT3 improves the efficacy of other chemotherapeutic agents for breast cancer, especially TNBC, remains to be further investigated." (PMID 37260179, 2023).
breast carcinoma (continued). "In addition, the effect of using DYNLT3 inhibitors on breast cancer recurrence and metastasis needs to be explored both in vitro and in vivo." (PMID 37260179, 2023). "Silence of DYNLT3 expression inhibited cell viability, migration, and invasion, and enhanced the proportion of apoptotic cells, while the proliferative, migratory and invasive abilities in DYNLT3‐overexpressed breast cancer cells were improved." (PMID 37260179, 2023). "Hence, this research was explored the role of DYNLT3 in breast cancer." (PMID 37260179, 2023). "In addition, a transcriptomics analysis showed that the transcriptome changes in age and breast cancer‐related genes (DYNLT3, P4HA3, and LX4) during aging may contribute to the progression of breast cancer." (PMID 37688399, 2023). "Taken together, it was suggested that DYNLT3 might act as a tumor‐promoter in breast cancer." (PMID 37260179, 2023). "DYNLT3 knockdown obviously suppressed cell growth, migration and invasion, and induced cell apoptosis in MDA‐MB‐231 and MCF‐7 breast cancer cells." (PMID 37260179, 2023). "To test the potential tumor-promoting roles of the two upregulated ABC genes DYNLT3 and P4HA3, we knocked down their expression in the basal-like breast cancer MDA-MB-231 cells and the luminal B breast cancer BT-474 cells." (PMID 32539762, 2020). "Knockdown of two upregulated genes (DYNLT3 and P4HA3) or overexpression of the downregulated ALX4 significantly reduced breast cancer cell proliferation, migration, and clonogenicity." (PMID 32539762, 2020). "Specifically, the upregulation of DYNLT3 and P4HA3 as well as the downregulation of ALX4 during aging promote breast cancer progression." (PMID 32539762, 2020). "With in vitro experiments, we showed that DYNLT3 and P4HA3 promoted breast cancer malignancy." (PMID 32539762, 2020). "DYNLT3, P4HA3, and ALX4 play significant roles in breast cancer progression." (PMID 32539762, 2020).
cervical cancer (3 papers, 2022 to 2025). A primary or metastatic malignant neoplasm involving the cervix. "Our study investigated the functions of DYNLT3 and its underlying molecular mechanism in cervical cancer." (PMID 35965516, 2022). "Another study also found that upregulation of DYNLT3 expression induced apoptosis and attenuated tumor metastasis in cervical cancer." (PMID 37260179, 2023). "The role of the dynein light chain Tctex-type 3 (DYNLT3) protein in the biological behavior of cervical cancer and its relative molecular mechanisms were investigated." (PMID 35965516, 2022). "DYNLT3 exerted inhibitory effects on cervical cancer by inhibiting cell proliferation, migration and invasion, promoting cell apoptosis in vitro, and inhibiting tumor growth and metastasis in vivo, possibly by suppressing the Wnt signaling pathway and the EMT." (PMID 35965516, 2022). "Our RT–PCR data also showed that DYNLT3 regulated the mRNA levels of Wnt3a in both cervical cancer cell lines." (PMID 35965516, 2022). "In this study, we reported that the expression level of DYNLT3 was lower in the human cervical cancer tissues than that in normal cervical tissues." (PMID 35965516, 2022). "Immunohistochemical staining was used to detect DYNLT3 protein expression in cervical cancer tissues." (PMID 35965516, 2022). "In the present study, DYNLT3 repressed proliferation and motility and stimulated cell apoptosis in cervical cancer." (PMID 35965516, 2022). "In addition, upregulation of DYNLT3 attenuated proliferation, reduced migration and invasion, and enhanced cell apoptosis in cervical cancer cells." (PMID 35965516, 2022). "In the present study, our results showed that DYNLT3 could inhibit Dvl2 expression in the Wnt pathway in cervical cancer." (PMID 35965516, 2022). "In addition, the major metastatic site of cervical cancer cells in mice was the lung, and downregulation of DYNLT3 expression increased cancer metastasis in vivo." (PMID 35965516, 2022). "Interestingly, there is a discrepancy of DYNLT3 expression assessed by IHC and western blotting in cervical cancer tissues and cell lines." (PMID 35965516, 2022). "Altogether, these results indicate that DYNLT3 may have a crucial function in the occurrence and development of cervical cancer, which may provide a new approach for combating cervical cancer." (PMID 35965516, 2022). "Our results demonstrated that DYNLT3 was expressed in the five cervical cancer cell lines." (PMID 35965516, 2022). "Advances in understanding over the mechanism of DYNLT3 in cervical cancer may benefit for the development of therapeutic strategies and novel treatment agents." (PMID 35965516, 2022). "Furthermore, the Wnt signaling pathway and EMT-related proteins were involved in the molecular mechanism of DYNLT3-mediated antitumor activity in cervical cancer." (PMID 35965516, 2022). "In addition, upregulation of DYNLT3 inhibited the tumor growth and metastasis in nude mice bearing human cervical cancer cells." (PMID 35965516, 2022). "Furthermore, the effects of DYNLT3 on the tumorigenicity and metastasis of cervical cancer in nude mice were analyzed by performing immunohistochemistry, and we found that the expression level of the DYNLT3 protein was higher in human normal cervical tissues than in cervical cancer tissues." (PMID 35965516, 2022). "The expression level of the DYNLT3 protein was highest in human normal cervical tissues among CIN1, CINII and cervical cancer tissues as determined by immunohistochemistry." (PMID 35965516, 2022). "It is important to note that our study does not provide the molecular mechanisms by which DYNLT3 regulates WNT pathway in cervical cancer cells." (PMID 35965516, 2022). "Characterizing the mechanisms by which DYNLT3 regulates the Wnt pathway and EMT process could improve our understanding of the tumorigenesis and may allow for the development of improved therapeutics for cervical cancer." (PMID 35965516, 2022).
salivary gland adenoid cystic carcinoma (2 papers, 2022 to 2023). An adenoid cystic carcinoma arising from the salivary gland. "DYNLT3 was also hypomethylated in salivary gland adenoid cystic carcinoma by genome‐wide screening." (PMID 37260179, 2023).
cervical tumor (1 paper, 2022). "In this study, DYNLT3 expression was measured by immunohistochemical (IHC) staining in cervical tumor specimens." (PMID 35965516, 2022).
esophageal squamous cell carcinoma (1 paper, 2022). Esophageal squamous cell carcinoma (ESCC) is a type of esophageal carcinoma (EC) that can affect any part of the esophagus, but is usually located in the upper or middle third. "In esophageal squamous cell carcinoma, DYNLT3 expression was significantly decreased and may serve as a tumor suppressive factor." (PMID 35965516, 2022). "However, the expression of DYNLT3 was downregulated in esophageal squamous cell carcinoma and may play a role in tumor suppression." (PMID 35965516, 2022).
glioma (1 paper, 2025). A benign or malignant brain and spinal cord tumor that arises from glial cells (astrocytes, oligodendrocytes, ependymal cells). "Other fc3 genes in the curated set, FERMT1, TMEM100, DYNLT3, EPHB1, IGFBP2, NNMT, and SH3GL2 all show direct evidence to a relationship with glioma biology and patient prognosis." (PMID 39941811, 2025).
hydronephrosis (1 paper, 2024). Collection of urine in the renal pelvis that results in dilatation of the renal pelvis and calyces. "Our data showed that in Tspan7 transgenic mice exhibiting a hydronephrosis-like pathology, not only Otc, the gene most adjacent to Tspan7, but also other contiguous genes, Xk, Dynlt3, and Mid1ip1, were affected." (PMID 39000307, 2024).
lung carcinoma (1 paper, 2022). "The major metastatic site of cancer cells was the lung, and the green fluorescence quantity of lung cancer was increased when the expression of DYNLT3 was downregulated." (PMID 35965516, 2022).
melanoma (1 paper, 2021). A malignant, usually aggressive tumor composed of atypical, neoplastic melanocytes. "Further studies will have to be performed to evaluate whether DYNLT3 protein levels are decreased in melanoma, at least in the context of melanoma patients with Parkinson’s." (PMID 33772156, 2021). "However, to the best of our knowledge, an association between DYNLT3 and melanoma has not been demonstrated." (PMID 33772156, 2021).
serous cystadenocarcinoma (1 paper, 2022). A malignant serous cystic neoplasm usually involving the ovary or the pancreas. "We previously found that the expression of DYNLT3 protein was low in normal ovarian epithelium and was increased in serous cystadenoma and serous cystadenocarcinoma." (PMID 35965516, 2022).
tumor (4 papers, 2012 to 2023). "The function of DYNLT3 in proliferation, apoptosis, migration, and invasion of tumor cells were explored by gain‐ and loss‐of function assays." (PMID 37260179, 2023). "DYNLT3 acted as a tumor‐promotor in ovarian carcinogenesis through impetus of cell proliferation and metastasis." (PMID 37260179, 2023). "Consistent with the in vitro results, the tumor growth rate was reduced and the volume of tumors was smaller after DYNLT3 knockdown." (PMID 37260179, 2023). "Up-regulation of DYNLT3 expression significantly inhibited tumor growth in a nude mouse model, while downregulation of DYNLT3 showed the opposite results." (PMID 35965516, 2022). "Compared with the control group, upregulation of DYNLT3 expression significantly inhibited tumor growth, while downregulation of DYNLT3 showed the opposite results (P< 0.05)." (PMID 35965516, 2022). "We found that knockdown of either DYNLT3 or P4HA3 significantly reduced the tumor malignant properties in both cell lines, in terms of cell proliferation, migration, and anchorage-independent colony formation efficiency in soft agar." (PMID 32539762, 2020). "Furthermore, nude mice xenograft models were established to confirm the role of DYNLT3 in tumor formation in vivo." (PMID 37260179, 2023). "DYNLT3 affect carcinogenesis might be related to the tumor types, exerting its oncogenic or tumor‐suppressive role in a tissue‐specific manner." (PMID 37260179, 2023). "However, DYNLT3 has been found to have tumor inhibition effect due to the reduced expression in esophageal squamous cell carcinoma by bioinformatics." (PMID 37260179, 2023). "Moreover, DYNLT3 knockdown inhibited tumor formation in vivo." (PMID 37260179, 2023). "In addition, whether DYNLT3 could affect tumor growth in vivo was studied by nude mice tumor models." (PMID 37260179, 2023). "In contrast to the knockdown of DYNLT3, the knockdown of P4HA3 significantly inhibited tumor progression and metastasis in vivo in terms of tumor volume, tumor weight, and total flux of luciferase activity in the lungs." (PMID 32539762, 2020). "DYNLT3 (dynein light chain Tctex-type 3) and HTATIP2 (HIV-1 Tat interactive protein 2) inhibit proliferation and survival, respectively, suggesting tumor suppressor activity." (PMID 22848398, 2012). "In contrast to the significant reduction of the malignant properties in vitro, we observed reduced tumor growth of DYNLT3 knockdown cells but with no statistical significance in comparison with the tumors formed the control cells in terms of tumor volume and tumor weight." (PMID 32539762, 2020). "Conventionally, MDA‐MB‐231 are characterized by the absence of E‐cadherin, however, DYNLT3 knockdown induced the expression of E‐cadherin in MDA‐MB‐231 cells, which maintained the adhesion between tumor cells and inhibited migration." (PMID 37260179, 2023).
cancer (3 papers, 2022 to 2023). A tumor composed of atypical neoplastic, often pleomorphic cells that invade other tissues. "We believe that the expression of DYNLT3 in cancer tissues is more important than that in cell lines." (PMID 35965516, 2022). "The number of colonies formations and cancer cells with BrdU incorporation was suppressed when DYNLT3 expression was silenced, while overexpression of DYNLT3 improved cell viability, and the number of colonies formation and BrdU incorporation cells were increased." (PMID 37260179, 2023). "Moreover, downregulation of DYNLT3 increased the cancer metastasis in the lung." (PMID 35965516, 2022).
DYNLT3 also shares sentences with these, for which no sentence is quoted: ciliopathies (1 paper); diabetes (1); Hydrocephalus (1); infection (1); neurologic disease (1); papilloma (1); Parkinson disease (1); Parkinson’s (1); serous cystadenoma (1).